PTK2 (protein tyrosine kinase 2)
Diseases named in the same sentence as PTK2 in open-access papers (continued):
Sharing a sentence is not in itself a finding about the gene and the disease.
bladder cancer (38 papers, 2012 to 2026). "In our study, the analysis of genes PRKCZ, PTK2, and IL-18 underscores their significant roles in bladder cancer carcinogenesis, progression, and survival outcomes." (PMID 39064604, 2024). "Silencing of circ-PTK2 inhibited the processes of cell proliferation and cell migration, whereas overexpression promoted proliferation and migration in bladder cancer." (PMID 34034740, 2021). "DNA methylation patterns such as protein tyrosine kinase 2 (PTK2) hypermethylation have been found to be associated with overall survival, whereas bladder cancer associated protein (BLCAP) hypomethylation is strongly associated with recurrence and cancer-specific death risk." (PMID 40282460, 2025). "Among these hub circRNAs, hsa_circ_0003221, hsa_circ_0000591, and hsa_circ_0000592 were derived from one gene (PTK2), and hsa_circ_0003221 recently has been reported as a potential biomarker for bladder cancer that promotes proliferation and migration of cancer cells." (PMID 31182759, 2019). "For instance, IL-6/JAK/STAT3 signaling enhances bladder cancer cell growth and is linked to targeted kinase inhibitor resistance, while TLR4 activation facilitates inflammation-associated carcinogenesis and liver cancer metastasis through protein tyrosine kinase 2 (PTK2) induction." (PMID 41573719, 2025). "Therefore, the functions of circ-PTK2 may be to those of circ_0003321 in bladder cancer, which acts as a cancer promoter." (PMID 34034740, 2021). "Additionally, in bladder cancer, PABPC1 enhances cell migration, invasion, and gemcitabine resistance through the PTK2-SETDB1 pathway." (PMID 41249135, 2025).
lung fibrosis (34 papers, 2011 to 2026). "In human patients with progressive pulmonary fibrosis, TGFB1-associated expression of fibroblastic PTK2 has been reported and experiments in a bleomycin-induced pulmonary fibrosis mouse model indicated that this kinase is related to fibroblastic proliferation, activation and collagen production." (PMID 27282780, 2016).
neuroblastoma (34 papers, 2010 to 2025). Neuroblastoma (NB) is the most common solid, extracranial childhood tumor. "Other genes (PTK2, NAV3, NAV1, FZD1 and ATRX), expressed in neuroblastoma and involved in cell invasion and migration were mutated at frequency ranged from 4% to 2%." (PMID 27009842, 2016). "Of note, non-silent somatic mutations were previously identified in PTK2 in one primary and one relapsed neuroblastoma." (PMID 27009842, 2016). "Interestingly, we found two driver mutations in PTK2, which encodes a focal adhesion kinase (FAK) protein, important for neuroblastoma tumor cell viability." (PMID 27009842, 2016).
lung adenocarcinoma (30 papers, 2009 to 2025). A carcinoma that arises from the lung and is characterized by the presence of malignant glandular epithelial cells. "Though, VEGFR2 shares with EGFR key intracellular partners such as SHC1, protein tyrosine kinase 2, and phospholipase C. EGFR-mutant lung adenocarcinoma patients who acquired EGFR-TKI treatment resistance may benefit from blocking VEGFR2 related angiogenesis and tumor growth." (PMID 31570733, 2019).
cervical carcinoma (29 papers, 2016 to 2025). A carcinoma arising from either the exocervical squamous epithelium or the endocervical glandular epithelium. "Given its anti-tumor effect, miR-520d-5p suppresses the proliferation and invasion of cervical cancer cells by regulating PTK2." (PMID 38100482, 2023). "PTK2 SPP1 were also related to the progression of cervical cancer." (PMID 36284631, 2022). "MiR-520d-5p is a tumor-suppressor by repressing PTK2 in cervical cancer." (PMID 34434890, 2021). "Our bioinformatics analyses show that miR-106b could promote cervical cancer progression by modulating the expression of GSK3B, VEGFA, and PTK2 genes." (PMID 30275981, 2018).
liver cancer (26 papers, 2007 to 2025). An epithelial or non-epithelial malignant neoplasm that arises from the liver. "Then, we employed the GEPIA database to further investigate the RNA expression of FAK (PTK2) in liver cancer tissues." (PMID 40958869, 2025). "Correspondingly, by employing gene signature analysis in online LIHC databases, we found that the mean expression of the gene set composed of KLF7, TLR4 and PTK2 was elevated in liver cancer tissues compared to normal livers, and further increased in liver cancer metastatic tissues." (PMID 37554278, 2023). "In conclusion, CircC16orf62 is an oncogene through the miR-138-5p/PTK2/Akt axis in HCC cells, indicating CircC16orf62 can be a therapeutic target with potentiality for liver cancer and a predictive marker for people with HCC." (PMID 34108451, 2021).
thyroid cancer (25 papers, 2012 to 2025). "This is different to the data obtained with thyroid cancer cells, where the PTK2 mRNA in FTC-133 thyroid cancer cells was differentially expressed in the TEXUS samples, but the FAK1 protein content was significantly reduced in RPM samples." (PMID 31261642, 2019). "A combination of VS-6063 (defactinib) and the PTK2 autophosphorylation inhibitor 1,2,4,5-benzenetetraamine tetrahydrochloride (Y15) synergistically decreased viability, clonogenicity, and attachment in thyroid cancer cell lines." (PMID 31791326, 2019).
endometrial cancer (20 papers, 2009 to 2025). Primary or metastatic malignant neoplasm involving the endometrium (mucous membrane that lines the endometrial cavity). "FAK is encoded by the PTK2 gene that can be amplified in cancers of the female reproductive system including endometrial cancer." (PMID 36409196, 2023). "Conversely, EMP2 was identified as an early predictor of endometrial cancers with unfavorable outcome by activation of protein tyrosine kinase 2 (PTK2 or FAK) and v-src avian sarcoma viral oncogene homolog (SRC)." (PMID 25940704, 2015).
ovarian tumor (18 papers, 2008 to 2025). "The PTK2 gene at 8q24.3, encoding focal adhesion kinase (FAK), is frequently amplified in breast, uterine, cervical, and ovarian tumors." (PMID 31478830, 2019). "Used the Kras, Myc, FAK (KMF) syngeneic ovarian tumor mouse model containing spontaneous FAK/PTK2 gene gains." (PMID 40475770, 2025). "Subsequently, the corresponding genes of the total enriched proteins were analyzed in cBioportal (datasets of ovarian tumors) to identify highly mutated elements directly associated with the claudin-4-interacting proteins, revealing BRD4, CCDC130, PTK2, and NDRG1 as the most mutated elements." (PMID 38867360, 2024).
diabetes (17 papers, 2008 to 2025). "Mutant forms of FAK impair insulin signalling in HepG2 cells and tail-vein injection of siRNA against the FAK gene (PTK2) leads to insulin resistance, concomitant with reduced protein kinase B (PKB, also known as Akt) phosphorylation in mouse models of diabetes." (PMID 29022062, 2018).
liver fibrosis (17 papers, 2017 to 2025). "Although these findings are novel, they are consistent with a previous study showing that focal adhesion kinase (FAK, also known as PTK2, another important FA protein) promotes HSC activation in vitro and liver fibrosis in vivo." (PMID 37667902, 2023).
metastatic cancers (16 papers, 2013 to 2024). A carcinoma which has spread from the original site of growth to another anatomic site. "Other frequently noted changes in connection with cell migration were a reduction in the active form of Focal Adhesion Kinase (FAK, PTK2), a key player in metastatic cancer, and upregulation of the epithelial marker E-cadherin, suggesting a reversal of the epithelial-mesenchymal transition." (PMID 34641429, 2021).
myeloma (15 papers, 2013 to 2024). "Our previous study observed that circular RNA protein tyrosine kinase 2 (circ-PTK2) was upregulated and correlated with worse clinical features and unfavorable prognosis in multiple myeloma (MM) patients." (PMID 34395238, 2021).
uveal melanoma (15 papers, 2012 to 2025). A melanoma derived from melanocytes of the uveal tract. "This locus harbors the oncogenes MYC, a commonly amplified uveal melanoma gene, and PTK2, a regulator of metastasis in uveal melanoma." (PMID 36860651, 2023). "Knowing this and as we have presented, uveal melanoma patients with monosomy of chromosome 3p (implicating VHL and BAP1) and gain of chromosome 8q (PTK2) have a worse prognosis." (PMID 40000790, 2025).
meningioma (13 papers, 2012 to 2026). A generally slow growing tumor attached to the dura mater. "In the meningioma model (Syn5 and Syn1), all three drugs induced merlin-deficient-specific kinase networks that included MAPK proteins, PTK2 (FAK1) and ephrin receptor proteins among other kinases." (PMID 29897904, 2018). "Similar to human schwannoma and meningioma, CUDC-907, GSK2126458 and Panobinostat also selectively induced MAP kinases, ephrin receptor kinases, and PTK2, suggesting that the mouse model recapitulates elements of the human tumor cell response to these drugs." (PMID 29897904, 2018).
viral infection (12 papers, 2014 to 2023). "Bai and coworkers demonstrated that viral infection induced an increase in the abundance of PPIA, which interacts and mediates protection from proteasomal degradation of PTK2." (PMID 35281454, 2022).
invasive breast carcinoma (11 papers, 2005 to 2022). A carcinoma that infiltrates the breast parenchyma. "PTK2 is linked to worse OS in ovarian and invasive breast cancer." (PMID 34497631, 2021). "For instance, the amplification of the gene encoding FAK, PTK2, has been observed in different types of tumors as the invasive breast cancer." (PMID 33562737, 2021).
acute myeloid leukemia (9 papers, 2010 to 2025). Acute myeloid leukemia (AML) is a group of neoplasms arising from precursor cells committed to the myeloid cell-line differentiation. "In acute myeloid leukemia (AML), abnormal expression of PTK2 is associated with poor prognosis and treatment resistance; therefore, exploring the role of PTK2 in APL is of great significance for understanding the relationship between lipid metabolism disorders and APL." (PMID 40040719, 2025).
astrocytomas (8 papers, 2010 to 2024). "This is consistent with in silico analysis of FAK/PTK2 mRNA levels that confirmed a lower expression in GBM compared with astrocytoma biopsies." (PMID 32349327, 2020).
Hypertension (8 papers, 2014 to 2025). The presence of chronic increased pressure in the systemic arterial system. "Rs11166990[A] upstream of PTK2 (coding for focal adhesion kinase), which also associates with the R amplitude in lead V1, associates with hypertension (MAF = 48%, OR = 0.97, P = 1.1 × 10−6), aortic valve stenosis (OR = 0.92, P = 2.1 × 10−4), and is known to associate with reduced risk of AF." (PMID 31641117, 2019).
lymphoma (8 papers, 2014 to 2024). A malignant (clonal) proliferation of B- lymphocytes or T- lymphocytes which involves the lymph nodes, bone marrow and/or extranodal sites. "Notably, expression of Ptk2/Fak was upregulated in both Lck-Dlx5- and Lck-MyrAkt2-derived lymphomas." (PMID 28122332, 2017). "These analyses suggested that co-expression of high levels of CD80 and PTK2 transcript occurs preferentially in cancer cell lines originating from patients with Burkitt’s Lymphoma, Hodgkin’s Lymphoma, Chronic Myeloid Leukemia, and Diffuse Large B-cell (DLBCL) Lymphoma." (PMID 31959281, 2020).
schwannoma (8 papers, 2016 to 2026). A benign, usually encapsulated slow growing tumor composed of Schwann cells. "To identify the target/s of crizotnib we employed activity-based protein profiling (ABPP), leading to identification of FAK1 (PTK2) as the relevant target of crizotinib inhibition in NF2-null schwannoma cells." (PMID 27363027, 2016). "In a compatible experiment using lysate prepared from schwannomas from a genetically engineered murine model (GEMM), Nf2flox/flox;Postn-Cre mice, a MIB competition assay identified FAK1 (PTK2) and GAK as the primary targets of brigatinib." (PMID 34264955, 2021). "Collectively, these data identify brigatinib as a direct and potent inhibitor of multiple kinases, including FAK1 (PTK2) and FAK2 (PTK2B), and novel targets, GAK and TNK2, in both arachnoid and schwannoma cells." (PMID 34264955, 2021). "In the human schwannoma model (HS01 and HS11), PTK2 and PTK2B (FAK1 and FAK2) were induced by all three drugs in a merlin-deficient-specific manner." (PMID 29897904, 2018). "Similarly, the non-RTK PTK2/FAK and the serine-threonine kinases GAK, RPS6KA3/RSK2, and MARK3 were also found to be greatly suppressed in brigatinib-treated schwannoma cells." (PMID 34264955, 2021).
hepatoblastoma (7 papers, 2015 to 2024). Hepatoblastoma (HB) is a malignant hepatic tumor and is the most common pediatric liver cancer. "The molecular pathways involved in H19-induced apoptosis in hepatoblastoma cells were discovered, and it was found that H19 suppressed the growth of hepatoblastoma cells by promoting apoptosis via the miR-675/FADD and miR-138/PTK2 signaling pathways." (PMID 38355574, 2024). "Finally, both the increased expression of PTK2 and reduced expression of FADD lead to the inhibition of cell apoptosis, thus promoting the tumorigenesis of hepatoblastoma." (PMID 38355574, 2024).
asthma (6 papers, 2020 to 2025). "Genetic markers, specifically protein kinase N2 and protein tyrosine kinase 2, along with breastfeeding duration, were also evaluated for their roles in asthma phenotypes." (PMID 39190449, 2024). "The CD1C, TLR7, PTK2, CD1E, CD1A, and ERBB2 genes had a higher rate of engaging protein interactions in the PPI for the moderate-to-severe asthma phenotype." (PMID 32512817, 2020).
metastatic melanoma (6 papers, 2013 to 2025). A melanoma that has spread from its primary site to another anatomic site. "In contrast, in the primary dataset, PTK2 generally exhibited positive correlations, particularly with macrophages, suggesting divergent roles in immune regulation between primary and metastatic melanoma." (PMID 40943183, 2025). "We found that PTK2 displayed consistent positive correlations with B cells, NK cells and monocytes, and negative correlations with CAFs and endothelial cells in metastatic melanomas." (PMID 40943183, 2025).
stomach adenocarcinoma (5 papers, 2016 to 2025). "Designing a case-control study including gastric adenocarcinoma and gastritis patients with and without Helicobacter pylori infection would lead to determinate of the correlations between ptk2 and mt2a genes expression with H. pylori infection in gastric antral epithelial cells." (PMID 36060520, 2022).
fibrosarcoma (4 papers, 2012 to 2025). A malignant mesenchymal fibroblastic neoplasm affecting the soft tissue and bone. "This occurred while exerting no apparent influence on the level and activation of P38, AKT, PTK2 protein tyrosine kinase 2 (PTK2), also known as focal adhesion kinase or FAK, steroid receptor coactivator, or Rapidly accelerated fibrosarcoma (RAF)." (PMID 30881341, 2019).
glomerular disease (4 papers, 2014 to 2021). "In addition, PTK2 promoted the expression of monocyte chemoattractant protein-1 and cell migration to accelerate the progression of various glomerular diseases." (PMID 32957963, 2020).
myocardial infarction (4 papers, 2017 to 2025). Gross necrosis of the myocardium, as a result of interruption of the blood supply to the area, as in coronary thrombosis. "The causal relationships revealed that NQO2 (1.047; 1.002–1.094; P = 0.042), CA6 (1.886; 1.015–1.162; P = 0.017), PTGDR (1.073; 1.012–1.137; P = 0.018), PTK2 (1.085; 1.002–1.176; P = 0.046), and CASP7 (1.080; 1.026–1.137; P = 0.003) were associated with high risk of myocardial infarction." (PMID 41573742, 2025). "Future in vivo studies using myocardial infarction animal models are therefore essential to confirm whether Quercetin truly exerts cardioprotective effects by modulating VEGFA, PTK2, and GGT1, as predicted in our bioinformatic and molecular docking analyses." (PMID 41573742, 2025).
acute promyelocytic leukemia (3 papers, 2019 to 2025). An aggressive form of acute myeloid leukemia (AML), characterized by arrest of leukocyte differentiation at the promyelocyte stage, due to a specific chromosomal translocation t(15;17) in myeloid cells. "Based on the results of bioinformatics analysis, to further explore the specific functions of PTK2 in acute promyelocytic leukemia (APL), we conducted cell experiments to validate further its role in cell proliferation, migration, and lipid metabolism." (PMID 40040719, 2025).
depression (3 papers, 2020 to 2025). "The genetic causality of JUN and PTK2 suggests that their activation in depression, upon ACR exposure, is likely an indirect consequence, mediated by the primary event of SIRT3 suppression and the resulting oxidative stress." (PMID 41150784, 2025). "Our Mendelian randomization analysis provides the first genetic evidence that JUN and PTK2 are causal risk factors for depression." (PMID 41150784, 2025). "Our findings demonstrate that ACR induces depression primarily through SIRT3 suppression, activating JUN/PTK2 pathways, suggesting its potential role in environmental toxicant-induced redox imbalance." (PMID 41150784, 2025).
Myocardial fibrosis (3 papers, 2017 to 2023). "On the other hand, the promoting of myocardial fibrosis with participation of MMP-9 is mediated by PTK2." (PMID 35053194, 2021). "Galectin-3 influences the development of myocardial fibrosis through an effect on the important intermediates of that regulation: phosphatase and tensin homolog (PTEN) and protein tyrosine kinase 2 (PTK2)." (PMID 35053194, 2021).
schizophrenia (3 papers, 2016 to 2023). A major psychotic disorder characterized by abnormalities in the perception or expression of reality. "An apparent close connection between the ketamine and BPC 157 was noted in the genes’ expression analysis in brain tissue, using Nos1, Nos2, Nos3, Plcg1, Prkcg, Ptgs2, and Ptk2 all associated with schizophrenia presentation." (PMID 35884767, 2022). "This was done with the genes’ expression analysis in brain tissue, using Nos1, Nos2, Nos3, Plcg1, Prkcg, Ptgs2, and Ptk2, all associated with schizophrenia presentation." (PMID 35884767, 2022).
acute pancreatitis (2 papers, 2024 to 2026). An acute inflammatory process that leads to necrosis of the pancreatic parenchyma. "In acute pancreatitis, miR-320-3p promotes cell proliferation by inhibiting the inflammatory response through the PTK2 axis." (PMID 39872394, 2024).
autism (2 papers, 2021 to 2022). Persistent deficits in social interaction and communication and interaction as well as a markedly restricted repertoire of activity and interest as well as repetitive patterns of behavior. "Moreover, the candidate genes PAK3, OCRL, DCX, PTK2, KCNQ3, SOX3, and LAMA1 were associated with autism, brain disease, Dent disease, and other conditions that present ID as a hallmark, corroborating our findings." (PMID 33922640, 2021).
gastric tumor (2 papers, 2016 to 2022). "Integrated analysis of public data from gastric tumors revealed frequent (10 – 20 %) amplification of the genes NFKBIE, PTK2, and PIK3CA, each of which resides in an ERBB2-derived subpathway network." (PMID 26955870, 2016).
laryngeal squamous cell carcinoma (2 papers, 2012 to 2024). A squamous cell carcinoma that arises from the larynx. "AC004943.2 facilitated the proliferation and migration and invasion of laryngeal squamous cell carcinoma cells through sponging miR‐135a‐5p and then activating the PTK2/PI3K pathway." (PMID 38545258, 2024).
lipid metabolism disorders (2 papers, 2018 to 2025). "In conclusion, this study reveals the changes in serum lipid levels in newly diagnosed APL patients and their association with PTK2 gene expression, expanding the understanding of the role of lipid metabolism disorders in the pathogenesis of APL." (PMID 40040719, 2025).